DDAH2 (DDAH family member 2, ADMA-independent)
Description:
Putative hydrolase with unknown substrate (Probable). Does not hydrolyze N(G),N(G)-dimethyl-L-arginine (ADMA) which acts as an inhibitor of NOS. In endothelial cells, induces expression of vascular endothelial growth factor (VEGF) via phosphorylation of the transcription factor SP1 by PKA in a process that is independent of NO and NO synthase (By similarity). Similarly, enhances pancreatic insulin secretion through SP1-mediated transcriptional up-regulation of secretagogin/SCGN, an insulin vesicle docking protein (By similarity). Upon viral infection, relocates to mitochondria where it promotes mitochondrial fission through activation of DNM1L leading to the inhibition of innate response activation mediated by MAVS.
Synonyms: DDAH; G6A; NG30; DDAHII; HEL-S-277
Tractability: PROTAC: ubiquitination databases record sites on it; its protein half-life has been measured.
Gene: Protein-coding gene on chromosome 6 (31,727,038 to 31,730,617, reverse strand). Ensembl gene ENSG00000213722.
Subcellular location: Cytoplasm; Mitochondrion
Subcellular location (Human Protein Atlas): Mitochondria
Gene Ontology:
Molecular function: dimethylargininase activity; protein binding
Biological process: negative regulation of apoptotic process; positive regulation of nitric oxide biosynthetic process
Cellular component: cytoplasm; extracellular exosome; mitochondrion
Genetic constraint (gnomAD): Loss-of-function variants: 8 observed, 26.06 expected, observed/expected ratio (o/e) 0.31, 90% interval 0.18 to 0.55. The upper end of that interval is the gene's LOEUF score, 0.55, which puts it in group 2 of 6, group 1 being the genes least tolerant of losing a copy. Missense variants: 281 observed, 402.18 expected, observed/expected ratio (o/e) 0.7, 90% interval 0.63 to 0.77. Synonymous variants: 151 observed, 179.4 expected, observed/expected ratio (o/e) 0.84, 90% interval 0.74 to 0.96.
Homologues: Orthologues: chimpanzee DDAH2 (99% identical), macaque DDAH2 (99% identical), pig DDAH2 (99% identical), dog DDAH2 (99% identical), mouse Ddah2 (97% identical), rabbit DDAH2 (97% identical), rat Ddah2 (97% identical), guinea pig DDAH2 (95% identical), zebrafish ddah2 (48% identical), Drosophila melanogaster CG1764 (33% identical), Caenorhabditis elegans T22B7.3 (18% identical), Caenorhabditis elegans F38H4.5 (16% identical). Paralogues in human: DDAH1 (51% identical).
Diseases named in the same sentence as DDAH2 in open-access papers:
DDAH2 is named in the same sentence as 87 diseases in open-access papers, as found by Europe PMC text mining. Sharing a sentence is not in itself a finding about the gene and the disease. The quoted sentences say what the papers report.
diabetes (10 papers, 2012 to 2025). "The analogical investigation in the present study suggests that PDTC treatment possesses similar effects or mechanisms to DDAH2 gene transfection underlying their amelioration of diabetes-induced impaired vasodilation." (PMID 28715444, 2017). "Examining data from the DIAGRAM+ (Diabetes Genetics Replication And Meta-analysis), we identified a variant (rs9267551) in the DDAH2 gene nominally associated with type 2 diabetes (P = 3×10−5)." (PMID 22558392, 2012). "DDAH2 gene polymorphism is associated with chronic kidney disease and diabetes mellitus." (PMID 24603538, 2014). "Taken together, these previous findings and our present data may suggest that DDAH2 underlies transcriptional regulation in pathophysiological conditions (myocardial infarction, diabetes, hypoxia, sepsis), and genetic variability in this gene may impair this regulatory role." (PMID 35207213, 2022). "Percentage comparison of genotypes (GG, GC, CC) of the DDAH2 G/C polymorphism across the STEMI (n=71), STEMI with diabetes (n=77), and healthy controls (n=75)." (PMID 40144407, 2025). "As predictor variable we adopted a factor produced by principal component analysis encompassing age, hsCRP, SBP, diagnosis of diabetes and DDAH2 rs9267551 genotype (χ2 = 90.8, P < 0.0001)." (PMID 35047582, 2021). "Previous studies indicated the common effects of DDAH2 on hypertension, diabetes, CVD is attributed to ADMA." (PMID 34283907, 2021). "We analyzed the distribution of NOS3 and DDAH2 genetic variants across three groups: Group I (STEMI without diabetes, n=71), Group II (STEMI with diabetes, n=77), and Group III (healthy controls, n=75)." (PMID 40144407, 2025). "As expected, it was found that the protective effect of PDTC against diabetes-induced impairment of vasodilation was very similar to that of ex vivo DDAH2 gene transfection, which increased vascular DDAH activity and improved the impairment of endothelium-dependant relaxation in diabetic rat aortas." (PMID 28715444, 2017). "Given this, the plasma levels of ADMA have been analyzed in individuals with glucose intolerance, insulin resistance and diabetes, elevated levels of the metabolite being associated with reduced DDAH activity, thoughout a polymorphism of the DDAH2 gene in case of type 2 diabetes." (PMID 23109853, 2012). "Alternatively, if DDAH2 does not metabolise ADMA, then development of ADMA-lowering therapies should be targeted towards DDAH1, while drug development targeting DDAH2 should be redirected towards its ADMA-independent biological effects in regulation of angiogenesis, diabetes, and immune responses." (PMID 37296100, 2023).
Sepsis (10 papers, 2006 to 2025). Sepsis is defined as life-threatening organ dysfunction caused by a dysregulated host response to infection. "In mice, knockouts (KOs) in DDAH2 result in increased mortality in a mouse model of sepsis, macrophage-specific DDAH2 KOs exhibit similar disease susceptibility to global KOs." (PMID 32318053, 2020). "Previous transgenic animal models have suggested that global and macrophage-specific knockout DDAH2 is associated with poor outcomes in murine models of sepsis." (PMID 30538005, 2018). "Global knockout of DDAH2 was associated with 80% lethality compared to wild-type animals when polymicrobial sepsis was induced, underlining the role of NO bioavailability in sepsis." (PMID 28709458, 2017). "In contrast, in pediatric sepsis, the DDAH2-449G polymorphism was associated with low ADMA concentration but with an increased likelihood of “cold” shock." (PMID 28709458, 2017). "Polymorphisms in the DDAH2 gene (OMIM #604744) have been associated with plasma ADMA levels in adult sepsis and vasopressor use following cardiac surgery." (PMID 22428028, 2012). "In human severe sepsis, a polymorphism in the DDAH-2 enzyme increased ADMA levels which were associated with increased severity of organ failure and early septic shock." (PMID 20421938, 2010). "Interestingly, in studies of polymicrobial sepsis in mice, global knockout of DDAH2 is associated with 12% 120-h survival compared to 53% survival in wild-type animals, underlining the important immunosuppression effect of ADMA in sepsis." (PMID 30231905, 2018). "Pilot studies have associated the rs805305 SNP of DDAH2 with ADMA concentrations in sepsis." (PMID 30538005, 2018). "To determine whether the DDAH2 polymorphisms were associated with susceptibility to severe sepsis/septic shock, we compared genotype distributions between septic and control patients." (PMID 22428028, 2012). "The GSEA findings indicated that CAPG and DDAH2 were strongly implicated in “FC gamma R-mediated phagocytosis” and “Ribosome” in both T2DM and sepsis, further indicating they share the same mechanism of immunometabolic reprogramming." (PMID 41050938, 2025). "At transcription and protein levels, CAPG and DDAH2 were significantly more highly expressed in the T2DM-sepsis model than in the controls." (PMID 41050938, 2025). "Deletion of DDAH-2 gene in an animal model of sepsis increased ADMA and produced excess mortality as compared to the wild-type animals." (PMID 35962414, 2022). "Further, we have shown that plasma ADMA levels are increased whereas DDAH2 expression in peripheral blood monocytes (PBMC) is reduced in patients with sepsis." (PMID 30231905, 2018). "In a series of 47 patients with severe sepsis, high ADMA concentration was associated with the DDAH2 -449G polymorphism." (PMID 30231905, 2018). "Agents that compete with ADMA for NOS (such as hArg) or that potentiate DDAH2 activity should be further investigated in sepsis." (PMID 28709458, 2017). "In another series of 47 patients with severe sepsis, high ADMA concentration was also associated with the DDAH2-449G polymorphism." (PMID 28709458, 2017). "We found that the −449G single nucleotide polymorphism (SNP) within the DDAH2 gene was associated with both decreased plasma ADMA and an increased likelihood of presenting with “cold” shock in pediatric sepsis." (PMID 22428028, 2012). "Under combined high-glucose and LPS stimulation, designed to mimic the inflammatory and metabolic stress of T2DM complicated with sepsis, its expression was markedly induced, supporting the role of DDAH2 as an inducible marker of systemic immune stress in T2DM and sepsis." (PMID 41050938, 2025). "Impaired endothelial function and defense mechanisms due to decreased NO production in endothelial and immune cells may be a mechanism linking hArg, ADMA, and DDAH2 expression with organ dysfunction and impaired immune response in sepsis." (PMID 28709458, 2017).
Sepsis (continued). "The predilection for DDAH2 in vascular tissue suggests that variability in expression or activity of this enzyme may contribute to hemodynamic changes observed in sepsis." (PMID 22428028, 2012). "CAPG and DDAH2, as key node genes, not only serve as early diagnostic biomarkers but also possibly influence diseases by the immune-metabolism pathway, proving a theoretical foundation for the development of stem cell-based combination therapies in T2DM and sepsis." (PMID 41050938, 2025). "This study found that a specific genetic polymorphism—the presence of at least one G allele at the −449 position—within the DDAH2 gene was associated with low plasma ADMA concentrations in children with severe sepsis or septic shock but not in non-septic controls." (PMID 22428028, 2012). "We sought to determine whether functional polymorphisms in DDAH2, which metabolizes the NO synthase inhibitor asymmetric dimethylarginine (ADMA), are associated with susceptibility to sepsis, plasma ADMA, distinct hemodynamic states, and vasopressor requirements in pediatric septic shock." (PMID 22428028, 2012). "Through a comprehensive analysis, CAPG and DDAH2 were found and those were significantly highly expressed in both T2DM and sepsis." (PMID 41050938, 2025). "In this study, we identified two shared stem cell-related biomarkers (CAPG and DDAH2) for T2DM and sepsis and further validated the expression of biomarkers through in vitro cell experiments." (PMID 41050938, 2025). "Subsequently, expression analysis revealed that in both training and validation sets for T2DM and sepsis, CAPG and DDAH2 were significantly highly expressed in the disease group." (PMID 41050938, 2025). "In sepsis pathophysiology, the concentration of ADMA in the plasma increases, and the expression and activity of DDAH2 in immune cells decrease." (PMID 41050938, 2025). "Functional enrichment analysis using GO and KEGG databases revealed that CAPG and DDAH2 exhibit convergent roles in T2DM and sepsis." (PMID 41050938, 2025). "Two common stem cell-related biomarkers (CAPG and DDAH2) and their common pathways between T2DM and sepsis were discovered, providing new insights for further molecular mechanism studies." (PMID 41050938, 2025). "In sepsis, CAPG and DDAH2 these genes showed broader functional repertoires, including Antigen processing and presentation, complement activation, and T cell receptor signalings." (PMID 41050938, 2025). "Gene entities shared between sepsis and severe sepsis response hubs are; TDRD9 – LIN7A, GPR84 – ENTPD7, PYCT1A and ZDHHC19, CD177 – DDAH2 and RGL4, SLC16A3 – DENND3 and MBD6, MYL9 – CMTM5, ITGB3, ITGA2B, NRGN, SELP and TREML1." (PMID 32318053, 2020). "The profile is somewhat similar in pediatric sepsis with connections between GPR84 and TDRD9 directly and indirectly through instead DDAH2 and with CD177 through C19orf59 and RGL4." (PMID 32318053, 2020). "These shared few commonalities between the different disease groups with the exception of DDAH2, RGL4, and ZDHHC19 in adult sepsis and pediatric septic shock." (PMID 32318053, 2020). "The −449G polymorphism in the DDAH2 gene was associated with both low plasma ADMA and an increased likelihood of presenting with “cold” shock in pediatric sepsis, but not with vasopressor requirement." (PMID 22428028, 2012). "Therefore, CAPG and DDAH2 were shared stem cell-related biomarkers for T2DM and sepsis." (PMID 41050938, 2025). "In summary, these findings highlight the complex roles of CAPG and DDAH2 in modulating immune cell functions in both T2DM and sepsis, suggesting that targeting these proteins may offer potential therapeutic strategies for managing inflammation and immune dysregulation in these diseases." (PMID 41050938, 2025).
Sepsis (continued). "Notably, the negative correlation between DDAH2 and CD8+ T cells was significant in both diseases, possibly reflecting its suppression of T cell toxicity through NO signaling, a mechanism that may have a double-edged effect in the autoimmune injury of T2DM and the immunosuppressive phase of sepsis." (PMID 41050938, 2025).
endothelial dysfunction (7 papers, 2014 to 2025). In vascular diseases, endothelial dysfunction is a systemic pathological state of the endothelium (the inner lining of blood vessels) and can be broadly defined as an imbalance between vasodilating and vasoconstricting substances produced by (or acting on) the endothelium. "Introduction and objectives: Nitric oxide synthase (NOS3) and dimethylarginine dimethylaminohydrolase 2 (DDAH2) polymorphisms are associated with reduced nitric oxide (NO) synthesis and endothelial dysfunction, increasing the risk of cardiovascular disease (CVD)." (PMID 40144407, 2025). "DDAH2 is considered an antiatherosclerotic molecule: in fact, hypermethylation of DDAH2 promoter, accompanied by its reduced expression, correlates with endothelial dysfunction in patients affected by Coronary Artery Disease58." (PMID 34413389, 2021). "Since DDAH is the key enzyme of endogenous ADMA degradation, inhibition of vascular DDAH activity has been reported to be involved in diabetic endothelial dysfunction, and DDAH1 or DDAH2 knockout mice showed endothelial dysfunction or endogenous ADMA accumulation." (PMID 28715444, 2017). "Therefore, modulating DNA methylation status of DDAH2 promoter may be a potential strategy for the treatment of endothelial dysfunction." (PMID 24934151, 2014). "Overexpression of DDAH2 could increase vascular DDAH activity and ameliorate hyperglycemia-induced endothelial dysfunction." (PMID 28715444, 2017).
Hypertension (7 papers, 2013 to 2021). The presence of chronic increased pressure in the systemic arterial system. "We conducted a case-control study on a Chinese population that included three ethnic groups (Han, Kazakh and Uygur), to systemically investigate associations between variations in the genes DDAH1 and DDAH2 and hypertension." (PMID 26786611, 2016). "In view of the genetic heterogeneity among ethnic groups, in the present study we aimed to systemically evaluate associations between the DDAH1 and DDAH2 variants and hypertension in three ethnic groups within the Chinese population (Han, Kazakh and Uygur)." (PMID 26786611, 2016). "Polymorphisms in the NOS3, DDAH1, DDAH2, and AGXT2 genes have previously been shown to relate to NO-mediated vascular function, hypertension, and mortality in a range of different patient populations." (PMID 34945057, 2021). "A large number of candidate genes for hypertension have now been widely studied and, among these, the genes DDAH1 and DDAH2 seem to have an influence on hypertension, since they play a fundamental role in maintaining endothelial function." (PMID 26786611, 2016). "Maternal citrulline supplementation prevented hypertension and kidney injury, increased the renal DDAH-2 protein level, and restored the levels of ADMA and NO in the STZ+Cit group." (PMID 23408977, 2013). "Contrary to what could be expected in llamas, we found a significant reduction in DDAH-2 expression in rats intolerant to the development of hypoxia-induced hypertension, which could explain the observed increase in ADMA." (PMID 29896110, 2018). "Furthermore, recent studies revealed the association between DDAH2 gene polymorphisms and CAD, type 2 diabetes and hypertension." (PMID 24934151, 2014).